BDNF (brain derived neurotrophic factor)
Diseases named in the same sentence as BDNF in open-access papers (continued):
Sharing a sentence is not in itself a finding about the gene and the disease.
depression (continued). "Presently, it is generally believed that a decrease in BDNF and TrkB protein levels is related to the occurrence of depression, and antidepressant treatment can improve the levels of BDNF and TrkB." (PMID 32009949, 2019). "Cranial irradiation leads to a decrease of BDNF in the hippocampus and studies in murine models of Rett syndrome or depression already have shown that FTY720 treatment increases hippocampal BDNF levels." (PMID 31354410, 2019). "An interactive effect on hippocampal volumes of early adversity and BDNF Met-carrier status has been described in major depressive disorder and psychosis." (PMID 30941021, 2019). "Accumulating evidence also suggests that SGK1 participates in the occurrence of depression via the glucocorticoid and brain-derived neurotrophic factor (BDNF) signaling pathway." (PMID 31632443, 2019). "In patients with depression, BDNF was down-regulated in the hippocampus and medial prefrontal cortex; which are closely related to emotional and cognitive functions." (PMID 31234814, 2019). "The excessive exposure to LPS induces TNF-α expression in the brain and suppresses BDNF expression, leading to the occurrence of anxiety/depression." (PMID 30979031, 2019). "Changes of BDNF levels inversely correlated with change in depressive symptoms assessed using the Calgary Depression Rating Scale in Schizophrenia (Pearson’s r = − 0.195; p = 0.018)." (PMID 31098654, 2019). "A follow-up MANOVA with only BSI measures of anxiety and depression revealed a highly statistically significant 5HTTLPR x BDNF interaction, F = 4.94, p = .02, Partial Eta Squared = 0.095." (PMID 31440532, 2019). "More recent animal studies have demonstrated that all animals displaying a depression-like phenotype showed low levels of BDNF after an intense stress (social defeat) and a state of oxidative stress associated with a BDNF decrease." (PMID 31156384, 2019). "Brain-derived neurotrophic factor (BDNF), an important member of the neurotrophic protein family, is important in the pathophysiology of depression." (PMID 30705774, 2019). "It has been commonly known that the role of BDNF-TrkB signaling in the pathogenesis and treatment mechanisms of depression." (PMID 32116688, 2019). "The alternation of BDNF/TrkB signaling pathway has been demonstrated to play a key role in the pathophysiology of depression and in the therapeutic mechanisms of antidepressant." (PMID 32009956, 2019). "The optimal cut-off value of serum BDNF levels as an indicator for screening of depression was estimated to be 12.28 ng/ml, which yielded a sensitivity of 72%, specificity of 85%, a true positive rate of 72%, and a false positive of 15%." (PMID 31234814, 2019). "Second, brain-derived neurotrophic factor (BDNF) and its receptor TrkB signaling plays a critical role in depression, pain and other neuropsychiatric diseases." (PMID 30705252, 2019). "Decreased hippocampal expression of BDNF is a well-recognized component of the neurobiology of depression, anxiety, and stress, and antidepressant treatment has been observed to increase levels of this messenger." (PMID 30719038, 2019). "Specifically, studies have demonstrated changes in DNA methylation at the BDNF promoter in blood samples from patients with Alzheimer’s disease (AD), major depression and schizophrenia." (PMID 32038165, 2019). "It has been demonstrated that depression is characterized by decreased levels of brain-derived neurotrophic factor (BDNF)." (PMID 34466472, 2019). "Based on these data we suggest that diabetes-induced neuroinflammation is, at least in part, responsible for decreased BDNF levels, which facilitate the development of depression-like behaviour." (PMID 31053872, 2019). "This was the first double-blind randomized placebo-controlled trial for depression that investigated changes in BDNF levels after an intervention with a psychedelic substance." (PMID 31231276, 2019).
depression (continued). "In the venlafaxine study, at randomisation, we observed a trend for positive correlation between BDNF levels (r = 0.19, p = 0.068) and severity of depression evaluated by HAMD." (PMID 31375659, 2019). "Decreased level of BDNF is observed in depression and its connection to hypertension has also been demonstrated with affecting the arterial baroreceptors, renin–angiotensin system and endothelial nitric oxide synthase." (PMID 30767081, 2019). "BDNF was also connected to psychiatric disorders prevalent in our population, including depression, PTSD, and substance use." (PMID 31491976, 2019). "It has been reported that LPS-induced inflammation decreased BDNF in the hypothalamus, contributing to depression-like behavior." (PMID 31251788, 2019). "Numerous clinical studies have demonstrated that BDNF is an important factor in the pathogenesis of depression." (PMID 31756901, 2019). "The differential methylation of CpG islands within the brain-derived neurotrophic factor (BDNF) gene has distinguished major depression patients from healthy controls in a Japanese population." (PMID 30781888, 2019). "Allelic group analyses indicated lowest risk, as measured by depression and anxiety, for allelic carriers of 5-HTTLPR-short and BDNF Met, followed by 5-HTTLPR-long and BDNF-Val, 5-HTTLPR-short and BDNF-Val, and 5-HTTLPR-long and BDNF-Met." (PMID 31440532, 2019). "One of the most studied neurotrophins is the BDNF, which plays an important role in synaptic plasticity and maintenance, and neuronal survival, supporting the hypothesis that alteration in neurotrophic signaling is a major factor underlying the pathophysiology of depression." (PMID 31125682, 2019). "Serum BDNF levels and demographic data of patients with major depressive disorder and healthy controls." (PMID 30794585, 2019). "We examined a battery of anxiety and depression behavior tests and showed that hypothalamic BDNF treatment significantly reduced anxiety‐ and depression‐like behaviors." (PMID 30585393, 2019). "Previous research has specifically confirmed that low serum levels of BDNF are related to high levels of depression." (PMID 30934558, 2019). "Nevertheless, our data indicated a more efficient effect of this antidepressant on BDNF/TrkB signaling in the mouse frontal cortex, stressing again the role of this structure in the pathogenesis of depression, as supported by other studies." (PMID 31004120, 2019). "Some other investigations suggest that low serum levels of BDNF are an abnormality index that is distinct during depression and normalizes during remission." (PMID 31234814, 2019). "Both in schizophrenia and in depression at the promoter I of BDNF DNA methylation at a specific CpG site is increased resulting in reduced BDNF gene transcription." (PMID 30767081, 2019). "It has been found that rTMS treatment improves symptoms of refractory depression, especially for agitation, by increasing the plasma level of BDNF." (PMID 32116552, 2019). "Brain derived neurotrophic factor (BDNF) controls the development of neuronal function and becomes ineffective in neurodegenerative disorders such as depression." (PMID 31817084, 2019). "Dysfunction of the BDNF/TrkB system is involved in the onset of brain disorders, such as Alzheimer, autism and depression." (PMID 31024262, 2019). "Agmatine showed antidepressant properties in Nrf2(+/+) mice via induction of Nrf2 and BDNF and was unable to reverse the depression-like effect in Nrf2 knockout (Nrf2(−/−)) mice." (PMID 31164818, 2019). "BDNF and proBDNF often have opposing actions; in fact, while BDNF promotes synaptic long-term potentiation and stress resistance, proBDNF enhances longterm depression." (PMID 31133872, 2019). "As observed for the role of SCFAs in depression, butyrate can normalize BDNF expression and depression-like behaviors in animals, through mechanisms involving BDNF-5HT synergistic modulation as well as HDAC inhibition and potentiation of 5HT transmission." (PMID 31861745, 2019).
depression (continued). "After binding with and activating TrkB, BDNF is regarded to suppress the pathophysiology of depression." (PMID 30940777, 2019). "Upon chronic HCE administration, the authors demonstrated enhanced levels of monoamines and the brain-derived neurotrophic factor (BDNF) in a rodent depression-like model together with increased sucrose preference in the sucrose preference test (SPT)." (PMID 31775329, 2019). "The BDNF-trkB system has been considered as a pharmacological target for both a hyperactive system in autism, and for underactivity in schizophrenia and depression." (PMID 31548888, 2019). "After a couple of weeks, the depression-like profile seemed to resolve, but half of the samples maintained low serum BDNF levels and oxidative stress." (PMID 31156384, 2019). "The prior studies investigated the possible relationship between PRL and BDNF genotypes and serum protein levels on our depression cohort." (PMID 31956308, 2019). "Higher incidence of depression has been found in patients with infection, and depression patients present increased levels of pro-inflammatory cytokines and decreased level of brain-derived neurotrophic factor (BDNF)." (PMID 32009956, 2019). "Anti-depressant treatments that restored or increased BDNF levels were able to alleviate symptoms of depression." (PMID 31881712, 2019). "Another RCT showed that an intervention using Go improved depression and increased serum levels of brain-derived neurotrophic factor (BDNF) in patients with AD." (PMID 30820242, 2019). "CUMS-induced depression-like behaviors are accompanied by a decrease in both the ratio of mature BDNF to proBDNF and the level of Kalirin-7 in the hippocampus." (PMID 31130853, 2019). "Within the hippocampus, mature BDNF facilitates long-term potentiation through TrkB, whereas long-term depression is facilitated by pro-BDNF through p75NTR activation." (PMID 31616373, 2019). "The BDNF-TrkB pathway in the nucleus accumbens of α7 nACHR knockout mice was demonstrated to be up-regulated, which was considered to be involved in their depression-like behavior." (PMID 31231295, 2019). "Rats fed with a n-3 PUFAs-deprived diet showed reduced levels of BDNF expression in the prefrontal cortex, an area of pivotal importance for the pathophysiology of depression, SCZ and ASD." (PMID 31861745, 2019). "Different studies have shown a possible relationship between low levels of BDNF and conditions such as depression, neurodegenerative disorders, Alzheimer disease, and dementia." (PMID 31317694, 2019). "Increased pro-BDNF levels in the prefrontal cortex and ventral tegmental area, and reduced levels of m-BDNF in the prefrontal cortex and hippocampus are observed in different studies using animal models of depression." (PMID 31231276, 2019). "In geriatric women, a higher BDNF DNA methylation level was detected in those with anxiety/depression compared to healthy controls." (PMID 31027379, 2019). "They reported that women with BDNF levels in the lowest three quartiles had 1.61 fold greater odds of antepartum depression in comparing to women with BDNF levels in the highest quartile." (PMID 31199848, 2019). "A reduced levels of brain BDNF was also observed as peripheral manifestations in patients with of depression." (PMID 31234814, 2019). "Chronic corticosterone (CORT) stress is an anxiety and depression inducing factor that involves the dysfunction of glucocorticoid receptor (GR), brain-derived neurotrophic factor (BDNF), and neuronal plasticity." (PMID 31888678, 2019). "Reductions in serum and plasma mature BDNF have been demonstrated in patients suffering from depression and in those who committed suicide." (PMID 30767081, 2019). "BDNF is widely present in the peripheral and central nervous systems and plays an important role in maintaining pain, depression, anxiety and memory-related functions." (PMID 31601968, 2019).
depression (continued). "Among the various responses induced by the glucocorticoid, the direct modulation of cortisol on BDNF appears to be extremely significant in understanding the etiology and treatment of major depression." (PMID 31231276, 2019). "But to understand the role of BDNF in depression, it is also necessary to further clarify the regulatory factors affecting BDNF expression, namely the upstream and downstream signaling pathways of BDNF in the nervous system." (PMID 31231295, 2019). "For instance, a traditional Korean medicine called Gyejibokryeong-hwan (GBH) has been reported to potentially regulate immune/endocrine dysfunction in mice to mitigate depression via activating the BDNF-cAMP-response element binding protein (CREB) pathway." (PMID 31569393, 2019). "Hippocampal biopsies of individuals with major depression revealed lower levels of BDNF and its receptor, tropomyosin receptor kinase B (TrkB)." (PMID 31053872, 2019). "BDNF and its receptor, tropomyosin-related kinase B (TrkB), are potential therapeutic targets for major depressive disorder." (PMID 32082151, 2019). "The present study revealed that depressed inpatients with a higher IR had higher serum BDNF levels at hospital discharge, suggesting a novel pathway to help understand the protective effects of religiosity on the brain with depressive disorders." (PMID 31572245, 2019). "It was also noted that maternal physical exercise during pregnancy enhances brain development, cognitive functions and BDNF levels of offspring and leads to better clinical outcomes in depressive disorder patients." (PMID 31199848, 2019). "Therapeutic interventions that augment neuroplasticity, via increases in BDNF, have been shown to reverse the pathological effects of depression." (PMID 29559928, 2018). "The precise mechanisms that the DNA methylation level of BDNF promoter I are involved in the pathogenesis of depression remains to be further clarified." (PMID 29636708, 2018). "A single bilateral infusion of BDNF into the dentate gyrus of hippocampus produced antidepressant-like effects in naive mice or in animal models of depression such as the learned helplessness." (PMID 30622454, 2018). "As reported, resveratrol increased BDNF expression and decreased behavioral symptoms in several animal models of depression." (PMID 30200269, 2018). "For example, reduced BDNF levels were reported in depressed patients and models of depression, and antidepressant treatment increased BDNF expression." (PMID 29887330, 2018). "Meanwhile, chronic antidepressant treatments can increase the BDNF level in vivo, and intrahippocampal and peripheral administration of BDNF produces antidepressant-like effects in rodent models with depression." (PMID 30410555, 2018). "BDNF expression is decreased in many neuropsychiatric and neurodegenerative diseases, including depression, bipolar disease, schizophrenia, Alzheimer’s disease, HD, SCA6 and Parkinson’s disease." (PMID 30718999, 2018). "In this study, the expression of BDNF, the pivotal marker of synaptic plasticity, was examined to reveal the molecular mechanism by which HE drives to normalize depression-like behavior." (PMID 29364170, 2018). "The alteration of IL-1β level, as well as that of BDNF, has been observed in major depressive patients, according to systematic Review and Meta-Analysis." (PMID 30042304, 2018). "BDNF serum levels have been determined in many studies to characterize changes in neuropsychiatric disorders such as depression, Alzheimer's disease and others." (PMID 29662942, 2018). "Biological variables, including inflammatory markers, cortisone, metabolic measures, BDNF, and vitamin D were able to predict only a chronic course of depression, although performance was worse than for clinical variables." (PMID 30397196, 2018). "BDNF levels in the NAc significantly increased in chronic methamphetamine-induced depression-like behavior." (PMID 30416533, 2018).
depression (continued). "Other neurotrophic factors, such as BDNF, have also highlighted the concerning role of neurogenesis in the pathogenesis of depression." (PMID 30369869, 2018). "It has been suggested that in addition to serving as a neurotrophic factor during development BDNF regulates synaptic plasticity and is involved in stress-induced hippocampal adaptation and the pathogenesis of depression." (PMID 30326843, 2018). "Over the last decades, convergent studies suggested that the BDNF/TrkB signaling pathway was a main actor in the development and course of mood disorders, in particular depression, as well as in the action of currently available antidepressants." (PMID 29961124, 2018). "Six meta-analyses of this data have found significantly lower levels of BDNF in bipolar disorder compared with healthy controls and people with unipolar depression, and lowered BDNF in bipolar mania and depression." (PMID 30113291, 2018). "Other studies have investigated the expression level of DNA methylation of BDNF in treatment-resistant major depressive patients, and the different expression in the methylation level of BDNF promoter I has been investigated." (PMID 29636708, 2018). "The decrease of BDNF level will impair the function of neuron and leads to the occurrence of depression." (PMID 30200295, 2018). "Accordingly, peripheral BDNF levels can serve as a biomarker for the successful treatment of depression and are relevant markers for the state of MDD." (PMID 30459647, 2018). "Multiple lines of evidence suggest that BDNF is integral to both the pathophysiology of depression and the therapeutic mechanisms of antidepressants." (PMID 29867510, 2018). "Depression induced by stress produces neurobiological alterations, along with decreases in brain-derived neurotrophic factor (BDNF) expression and hippocampal neurons proliferation, survival, and maturation." (PMID 30323763, 2018). "Brain-derived neurotrophic factor (BDNF) is a critical effector of depression-like behaviors and antidepressant responses." (PMID 30429764, 2018). "BDNF levels are lower in humans with depression, bipolar disorder, schizophrenia, and dementia compared to age-matched controls." (PMID 29944703, 2018). "To confirm the effect of GBH treatment in our model of reserpine-induced depression, we examined BDNF and p-CREB expression in the hippocampus via immunofluorescence analysis." (PMID 30046601, 2018). "Single administration of HBK-15 (1.25 mg/kg) and ketamine (1 mg/kg) reversed depression-like behavior and regulated decreased BDNF level in the hippocampus in corticosterone-treated mice." (PMID 28550529, 2018). "In animal models, it has been shown that the expression of BDNF is downregulated by exposure to stress (an important factor contributing to depression) and can be restored by antidepressant treatment." (PMID 30294251, 2018). "Experimental and clinical data indicate a central role for the brain-derivedneurotrophic factor (BDNF) in the pathogenesis of depression." (PMID 30397531, 2018). "The attenuation effects on CUMS-induced depression-related and anxiety-related behaviors were attributed to the elevated BDNF pathway." (PMID 30410442, 2018). "Brain-derived neurotrophic factor (BDNF) is a useful serum marker for evaluation of the pathophysiology of mood disorders, depression, and a range of other psychiatric diseases." (PMID 29321655, 2018). "The sample size of this feasibility study is small; thus, even though the exercise group experienced a concomitant decrease in depression severity and increase in plasma BDNF, our results must be considered preliminary." (PMID 29559928, 2018). "And it has been identified that BDNF is involved in the pathogenesis of a wide range of psychiatric disorders, including depression, schizophrenia, and anxiety disorder." (PMID 29636708, 2018). "It has also been demonstrated that BDNF concentration is reduced in individuals with major depression and increases after antidepressant drug treatment." (PMID 29896439, 2018).